BBS4 (Bardet-Biedl syndrome 4)
Description:
The BBSome complex is thought to function as a coat complex required for sorting of specific membrane proteins to the primary cilia. The BBSome complex is required for ciliogenesis but is dispensable for centriolar satellite function. This ciliogenic function is mediated in part by the Rab8 GDP/GTP exchange factor, which localizes to the basal body and contacts the BBSome. Rab8(GTP) enters the primary cilium and promotes extension of the ciliary membrane. Firstly the BBSome associates with the ciliary membrane and binds to RAB3IP/Rabin8, the guanosyl exchange factor (GEF) for Rab8 and then the Rab8-GTP localizes to the cilium and promotes docking and fusion of carrier vesicles to the base of the ciliary membrane. The BBSome complex, together with the LTZL1, controls SMO ciliary trafficking and contributes to the sonic hedgehog (SHH) pathway regulation. Required for proper BBSome complex assembly and its ciliary localization. Required for microtubule anchoring at the centrosome but not for microtubule nucleation. May be required for the dynein-mediated transport of pericentriolar proteins to the centrosome.
Tractability: Antibody: its Gene Ontology location is reachable by antibodies, with medium confidence. PROTAC: ubiquitination databases record sites on it; its protein half-life has been measured.
Gene: Protein-coding gene on chromosome 15 (72,686,186 to 72,742,006, forward strand). Ensembl gene ENSG00000140463.
Subcellular location: Cytoplasm, cytoskeleton, microtubule organizing center, centrosome; Cell projection, cilium membrane; Cytoplasm; Cytoplasm, cytoskeleton, microtubule organizing center, centrosome, centriolar satellite; Cell projection, cilium, flagellum; Cell projection, cilium
Subcellular location (Human Protein Atlas): Cytosol; Flagellar centriole; Principal piece; Acrosome; Annulus; Perinuclear theca
Pathways (Reactome):
Organelle biogenesis and maintenance: BBSome-mediated cargo-targeting to cilium
Gene Ontology:
Molecular function: alpha-tubulin binding; beta-tubulin binding; dynactin binding; protein binding; protein-macromolecule adaptor activity; RNA polymerase II-specific DNA-binding transcription factor binding
Biological process: centrosome cycle; maintenance of protein location in nucleus; microtubule anchoring at centrosome; mitotic cytokinesis; protein localization to centrosome; protein localization to cilium; regulation of cytokinesis; adult behavior; brain morphogenesis; cerebral cortex development; cilium assembly; dendrite development; fat cell differentiation; heart looping; hippocampus development; melanosome transport; microtubule cytoskeleton organization; negative regulation of appetite by leptin-mediated signaling pathway; neural tube closure; non-motile cilium assembly; photoreceptor cell maintenance; positive regulation of cilium assembly; regulation of cilium beat frequency involved in ciliary motility; regulation of lipid metabolic process; retina homeostasis; and 6 more
Cellular component: BBSome; centriolar satellite; centriole; centrosome; ciliary basal body; ciliary membrane; ciliary transition zone; cilium; motile cilium; non-motile cilium; pericentriolar material; cytosol; cytoplasm; membrane; nucleus; photoreceptor connecting cilium; photoreceptor inner segment; photoreceptor outer segment
Genetic constraint (gnomAD): Loss-of-function variants: 45 observed, 60.56 expected, observed/expected ratio (o/e) 0.74, 90% interval 0.58 to 0.95. The upper end of that interval is the gene's LOEUF score, 0.95, which puts it in group 4 of 6, group 1 being the genes least tolerant of losing a copy. Missense variants: 580 observed, 555.78 expected, observed/expected ratio (o/e) 1.04, 90% interval 0.97 to 1.12. Synonymous variants: 196 observed, 200.2 expected, observed/expected ratio (o/e) 0.98, 90% interval 0.87 to 1.1.
Homologues: Orthologues: chimpanzee BBS4 (100% identical), macaque BBS4 (98% identical), pig BBS4 (91% identical), mouse Bbs4 (90% identical), rat Bbs4 (90% identical), dog BBS4 (88% identical), rabbit BBS4 (85% identical), zebrafish bbs4 (73% identical). Paralogues in human: CFAP70 (18% identical), TMTC2 (16% identical), TMTC1 (16% identical), TTC7A (15% identical), TMTC3 (14% identical), TTC16 (14% identical), TTC7B (14% identical), IFT88 (14% identical), OGT (14% identical), TTC6 (13% identical), TMTC4 (13% identical), TTC13 (11% identical), and 2 more.